PRMT1 (protein arginine methyltransferase 1)
Diseases named in the same sentence as PRMT1 in open-access papers (continued):
Sharing a sentence is not in itself a finding about the gene and the disease.
Obesity (10 papers, 2020 to 2025). Accumulation of substantial excess body fat. "Despite elevated PRMT1 expression in response to a HFD or obesity, SAM deficiency restricted its methylation activity." (PMID 41256732, 2025). "Socs3, Mmp9 and Prmt1, which had elevated expression levels in obesity that were reversed by weight loss, had decreased expression in ABA and remained decreased in WR." (PMID 37582711, 2023). "Furthermore, we summarize the current knowledge regarding the role of PRMT1 in metabolic reprogramming, lipid metabolism, and glucose metabolism and describe the association of PRMT1 with numerous metabolic pathologies such as obesity, liver disease, and type 2 diabetes." (PMID 40001488, 2025). "The researchers detected a profusion of PRMT1 expression in white adipose tissue (WAT) in mice fed a high-fat diet that mimics the diet of humans with obesity." (PMID 40001488, 2025). "A recent study further revealed that the depletion of Prmt1 in adipocytes impairs glucose homeostasis in cases of diet-induced obesity." (PMID 39063139, 2024). "Recently, PRMT1 was revealed to play a pivotal role in metabolic diseases, including insulin resistance and obesity." (PMID 39063139, 2024). "Of note, the pathway for cytochrome P450, which has been shown to protect mice against HFD-induced obesity, was also significantly enriched among the DEGs, suggesting a potential role of PRMT1 in lipid metabolism." (PMID 38835047, 2024). "Collectively, these discoveries highlight a critical role of PRMT1 in adipogenesis and provide potential therapeutic targets for the treatment of obesity." (PMID 35921899, 2022). "Our findings suggest that the increase in PRMT1 expression in liver in obesity serves as a compensatory mechanism for the decrease in SAM to alleviate HFD-induced hepatic steatosis and liver damage by promoting fatty acid oxidation." (PMID 35401831, 2022). "Moreover, recent study has reported that adipocyte-specific depletion of PRMT1 impairs glucose homeostasis in diet-induced obesity, but the regulatory mechanism of PRMT1 in adipogenesis requires further elucidation." (PMID 35921899, 2022). "Indeed, a recent report has demonstrated that PRMT1 plays a regulatory role in the thermogenic fat function and could represent a new therapeutic strategy against human obesity and comorbidities." (PMID 34822417, 2021). "In adipose tissue, PRMT1 is prominently upregulated in response to a HFD and in human obesity." (PMID 41256732, 2025). "There are no previous reports on the role of PRMT1 and PRMT6 in obesity-induced skeletal muscle atrophy." (PMID 32316567, 2020).
heart failure (9 papers, 2018 to 2025). Inability of the heart to pump blood at an adequate rate to meet tissue metabolic requirements. "Loss of PRMT1 in cardiomyocytes causes multifunctional CaMKII dysregulation, resulting in dilated cardiomyopathy and heart failure." (PMID 36304554, 2022). "In summary, PRMT1 deficiency in cardiomyocytes causes dysregulation of CaMKII resulting in dilated cardiomyopathy and heart failure." (PMID 30504773, 2018). "In conclusion, PRMT1 deficiency in cardiomyocytes causes CaMKII dysregulation resulting in dilated cardiomyopathy and heart failure." (PMID 30504773, 2018). "Taken together, these data suggest that the myocardium-specific deletion of PRMT1 causes dilated cardiomyopathy with a severe fibrosis and cell death, eventually leading to heart failure." (PMID 30504773, 2018). "Mice with PRMT1 knockout exhibit characteristics of heart failure, highlighting the importance of PRMT1 in regulating alternative splicing in vivo and maintaining cardiac homeostasis." (PMID 38326807, 2024). "Mice of PRMT1-depletion in heart developed severe dilated cardiomyopathy and progressed to heart failure 2 months after birth." (PMID 37951845, 2023). "Similar result was reported in patient with heart failure, which PRMT1 level was significantly declining in heart tissue." (PMID 37951845, 2023). "Cardiac-specific PRMT1 ablation exhibits the contractile dysfunction around 5-weeks of age and die within 2-months with dilated cardiomyopathy and heart failure." (PMID 31787756, 2019). "The ablation of PRMT1 function in myocardium results in a rapid progression to heart failure with dilated cardiomyopathy." (PMID 30504773, 2018). "Our data show that the level of PRMT1 protein is reduced in human heart failure, supporting the notion that the level of cellular PRMT1 must be precisely maintained and controlled for cardiac function." (PMID 30504773, 2018). "Mice null for cardiac PRMT1 exhibit a rapid progression to dilated cardiomyopathy and heart failure within 2 months, accompanied by cardiomyocyte hypertrophy and fibrosis." (PMID 30504773, 2018). "This study provides compelling evidences that PRMT1 depletion induces myocardial hypertrophy and heart failure via CaMKII dysregulation." (PMID 30504773, 2018). "Whether PRMT1 activation can protect against DOX-induced heart failure has to be proven in future studies." (PMID 35260914, 2022). "Consistently, PRMT1 is downregulated in heart failure patients." (PMID 30504773, 2018). "The beneficial effects of PRMT1 on CaMKII in cardiomyocytes indicate that arginine methylation of CaMKII may provide a novel therapeutic strategy for the treatment of heart failure." (PMID 30504773, 2018). "Moreover, PRMT1’s modulation of cardiac IKs activity may be a crucial target for preventing excessive prolongation of action potential duration and arrhythmias in heart failure patients." (PMID 38326807, 2024). "In addition, PRMT1 promoted asymmetric di-methylation of CaMKII at R9 and R275 sites, thus hindered the activation of CaMKII and protected against cardiac hypertrophy and heart failure." (PMID 37951845, 2023). "Furthermore, through literature research, we found that some MYC target genes were previously reported involving the development of heart failure, including STAT3, PRMT1, PRKCH and HSPA4." (PMID 32460775, 2020). "Consistently, the level of PRMT1 protein was significantly reduced in ventricular myocardium from heart-failure patients, compared to non-failing hearts." (PMID 30504773, 2018). "The rapidly progressing cardiomyopathy and heart failure observed in PRMT1 cKO within 8-weeks after birth likely is due to its role in the control of critical regulators for cardiac function such as CaMKII and ATF4 that are directly contributing to ER stress and heart failure." (PMID 31787756, 2019). "However, considering that PRMT1 is the major cellular PRMT and heart failure of cKO mice rapidly progressed, we do not rule out the involvement of other pathways." (PMID 31787756, 2019).
liver cancer (9 papers, 2017 to 2026). An epithelial or non-epithelial malignant neoplasm that arises from the liver. "Our previous study confirmed that PRMT1 is significantly elevated in patients with liver cancer and is associated with prognosis." (PMID 41501793, 2026). "PRMT1 exhibits aberrant expression in liver cancer patient samples, where its levels are correlated with HCC progression, modulation of the tumor immune microenvironment, and dysregulation of fatty acid metabolism." (PMID 41256732, 2025). "Furthermore, PRMT1 knockdown downregulates TGF‐β1 and phospho‐Smad2/3, while its overexpression has the opposite effect, confirming that PRMT1 facilitates EMT in liver cancer via the TGF‐β1/Smad pathway and highlighting its therapeutic potential." (PMID 41256732, 2025). "Similarly, in liver cancer, PRMT1 knockdown reverses the EMT phenotype, downregulating mesenchymal markers (Vimentin, Snail, N‐cadherin) and upregulating E‐cadherin." (PMID 41256732, 2025). "Here, we reported PRMT1 as a regulator of Hippo‐YAP activity in liver cancer." (PMID 39367565, 2024). "In summary, elevated PRMT1 expression in HCC tissues, coupled with its prognostic value and involvement in various molecular pathways, underscores its potential as both a diagnostic marker and therapeutic target in liver cancer." (PMID 38326807, 2024). "Interestingly, a lack of PRMT1 causes hepatocyte proliferation, and the function of PRMT1 is strongly inhibited by alcohol, suggesting that the PRMT1–HNF4α axis plays a significant role in alcohol-related liver cancer development." (PMID 34771521, 2021). "In the univariate analysis, significant prognostic indicators of HCC overall survival included the PRMT1 signature, alpha-fetoprotein (AFP), tumor size, and Barcelona Clinic Liver Cancer (BCLC) stage." (PMID 29383172, 2017). "In alcohol-induced liver cancer cells, the normal biological function of PRMT1 may not be maintained, and instead, it may exhibit characteristics that promote cancer cell proliferation, invasion, and metastasis, thereby exerting a carcinogenic effect." (PMID 38326807, 2024).
esophageal squamous cell carcinoma (8 papers, 2019 to 2025). Esophageal squamous cell carcinoma (ESCC) is a type of esophageal carcinoma (EC) that can affect any part of the esophagus, but is usually located in the upper or middle third. "Recent studies have unveiled that PRMT1, a protein arginine methyltransferase, is highly expressed in esophageal squamous cell carcinoma (ESCC) and is associated with poor prognosis." (PMID 38326807, 2024). "This was shown in a study by Zhao and colleagues, who investigated the effect of PRMT1 in esophageal squamous cell carcinoma (ESSC)." (PMID 40001488, 2025). "PRMT1 promoted tumor-initiating capability in esophageal squamous cell carcinoma through histone arginine methylation." (PMID 34683150, 2021). "Mechanistically, PRMT1 methylates the DNA-binding domain (DBD) of Gli1, known as glioma-associated oncogene homolog 1, thereby potentiating its transcriptional activity, promoting the growth and migration of esophageal squamous cell carcinoma cells." (PMID 38326807, 2024). "Similar findings can be observed for esophageal CSCs, in which the highly expressed PRMT1 in esophageal squamous cell carcinoma (ESCC) catalyzed the histone H4R3 arginine asymmetric demethylation to activate the Wnt/β-catenin and Notch signaling pathways for stemness maintenance." (PMID 37298124, 2023). "Likewise, PRMT1 was found to be overexpressed in triple negative breast cancer (TNBC) and oesophageal squamous cell carcinoma (ESCC)." (PMID 39703687, 2024).
osteosarcoma (8 papers, 2016 to 2024). A usually aggressive malignant bone-forming mesenchymal neoplasm, predominantly affecting adolescents and young adults. "In conclusion, understanding PRMT1’s role in osteosarcoma tumorigenesis, its interactions with translation-associated genes, and its involvement in the apoptosis pathway provides insights for developing targeted therapies against osteosarcoma." (PMID 38326807, 2024). "The understanding of PRMT1’s mechanism in osteosarcoma tumorigenesis and the identification of exploitable vulnerabilities for targeted therapy are of utmost importance in the quest for effective treatment strategies." (PMID 38326807, 2024). "Methylation of STAT3 at arginine 688 by PRMT1 promoted its transcriptional activation, contributing to osteosarcoma malignancy." (PMID 38326807, 2024). "TIPE1, by targeting the catalytic domain of PRMT1, inhibited its methyltransferase activity and suppressed osteosarcoma progression." (PMID 38326807, 2024). "In this study, we showed that TIPE1 inhibits STAT3 transactivation and expression via PRMT1, resulting in decreased osteosarcoma tumorigenesis and progression." (PMID 36151091, 2022). "We thus postulated that TIPE1 inhibits the tumorigenesis and progression of osteosarcoma by regulating PRMT1-mediated STAT3 expression." (PMID 36151091, 2022). "We reported that TIPE1 inhibited cell proliferation, migration and invasion in the carcinogenesis of osteosarcoma by inhibiting PRMT1-mediated STAT3 function." (PMID 36151091, 2022). "Taken together, these data showed that TIPE1 inhibits the malignant transformation of osteosarcoma through PRMT1-mediated STAT3 arginine methylation and ultimately decreases the development and metastasis of osteosarcoma." (PMID 36151091, 2022). "It was found that PRMT1-mediated H4R3me2a could enhance c-Myc expression, activating the mTOR signaling pathway and promoting osteosarcoma progression." (PMID 38326807, 2024). "Similarly, PRMT1 significantly restored the osteosarcoma cell migration rate that was previously suppressed by TIPE1." (PMID 36151091, 2022). "More importantly, we demonstrated that overexpression of PRMT1 rescued TIPE1-caused the inhibition of cell proliferation, and administration of STAT3 inhibitor can abolish this inhibition, indicating that TIPE1 inhibits osteosarcoma proliferation primarily via PRMT1-mediated STAT3 suppression." (PMID 36151091, 2022). "Therefore, combined with previous studies, we believe that PRMT1 might be the most likely candidate protein that interacts with TIPE1 to participate in the procession of osteosarcoma." (PMID 36151091, 2022). "Three PRMTs (i.e., PRMT1, PRMT4/CARM1 and PRMT5) have each been shown to control vitamin D3-dependent transcription in osteosarcoma cells via interactions with SRC-1/NCOA1, whereas PRMT5 binds to the SWI/SNF component BRG1/SMARCA4 in different cell types." (PMID 37593409, 2023). "PRMT1, PRMT4/CARM1, PRMT5 and PRMT7 are prevalent isoforms that are functionally expressed in myogenic cells and osteosarcoma cells." (PMID 37593409, 2023). "Another report also showed that PRMT1 can methylate and activate STAT3 and contributes to osteosarcoma progression." (PMID 36151091, 2022). "In human osteosarcoma cells (U2OS), PRMT1 was predominantly expressed in the cytoplasm, whereas it was primarily expressed in the nucleus in human breast adenocarcinoma cells (MCF-7)." (PMID 28671608, 2017). "The degradation of PRMT1 by GGA through the HSP70-CHIP-mediated proteasomal pathway was found to induce cell apoptosis triggered by FAS, suggesting potential therapeutic approaches for osteosarcoma." (PMID 38326807, 2024).
osteosarcoma (continued). "Our findings on the distinct functions of PRMT1, PRMT4/CARM1 and PRMT5 complement and extend previous studies that examined the contribution of PRMTs and their cognate epigenetic modifications in vitamin D3-dependent transcriptional regulation in rat osteosarcoma cells." (PMID 37593409, 2023). "To determine whether TIPE1 inhibits osteosarcoma tumorigenesis and progression via PRMT1 specifically, we transfected TIPE1 into osteosarcoma cells with or without PRMT1." (PMID 36151091, 2022).
renal fibrosis (8 papers, 2022 to 2025). A final common manifestation of a wide variety of chronic kidney diseases characterized by glomerulosclerosis and tubulointerstitial fibrosis. "Consistent with PRMT1 inhibition, PRMT3 deficiency inhibits ADMA production and increases renal fibrosis, blocked by intra-renal injection of ADMA." (PMID 40869261, 2025). "In the UUO model, PRMT1 contributes to renal fibrosis by modulating the TGF-β/SMAD3 pathway, a process attenuated by the inhibitory effects of AMI-1." (PMID 38929505, 2024). "This improvement is attributed to inhibiting nitric oxide (NO) levels in HK-2 cells, whereas the inhibitor PT1001B, which targets PRMT1, exacerbates renal fibrosis." (PMID 38929505, 2024). "PRMT1 has also been shown to affect NO production and reduce renal fibrosis through AMDA, and inhibition of PRMT1 with PT1001B can increase this pathological progression." (PMID 35559246, 2022). "Additionally, several reports showed that PRMT1-mediated methylation promotes renal fibrosis, activates renal fibroblasts, and induces EMT in renal tissue from UUO mouse models." (PMID 41226322, 2025). "Some studies indicate that PRMT1 is upregulated in angiotensin II‐induced renal fibrosis." (PMID 37525933, 2023). "Excessive hyperglycemia can activate protein kinase RNA-like endoplasmic reticulum kinase (PERK) and transcription factor 6 (ATF6) by upregulating H4R3me2a, promoting EMT and ER stress, accelerating PTEC apoptosis, and aggravating renal fibrosis by upregulating PRMT1 expression." (PMID 36817133, 2023). "Protein arginine methyltransferase 1 (PRMT1), which is the primary enzyme responsible for the asymmetric arginine methylation of histone proteins, plays a pronounced function in renal fibroblast activation and the development of renal fibrosis by activating the TGF-β/Smad3 signaling pathway." (PMID 38671903, 2024). "In recent research, PRMT1 was reported to mediate BRD4 arginine methylation and phosphorylation thus promoting partial epithelial-mesenchymal transformation and renal fibrosis." (PMID 40612681, 2025). "In contrast, nebivolol decreased the expression of PRMT1, ADMA, and DDAH2 and lessened renal fibrosis and capillary damage, and improved renal function; the exact mechanism is not known." (PMID 36817133, 2023). "PRMT1 can promote renal fibrosis injured by left ureteral obstruction through the TGF‐β1/Smad3 signaling pathway, suggesting a key role of PRMT1 in TGF‐β1/Smad3 signaling." (PMID 37525933, 2023). "In UUO mice models, Previous studies in our group find that PRMT1 and H4R3me2a are up-regulated in the UUO mice models, and inhibition of PRMT1 via AMI-1 can inhibit the activation of TGF-β/Smad3 signaling pathway and alleviate renal fibrosis." (PMID 35559246, 2022). "PRMT1 inhibitor reduced ADMA production, but increased renal fibrosis in UUO-treated mice." (PMID 40869261, 2025). "PRMT1 induces endoplasmic reticulum (ER) stress and EMT to promote renal fibrosis in the DN model." (PMID 38929505, 2024).